CYP1B1 (cytochrome P450 family 1 subfamily B member 1)
Diseases named in the same sentence as CYP1B1 in open-access papers (continued):
Sharing a sentence is not in itself a finding about the gene and the disease.
tumor (continued). "As to whether kynurenine/AhR/CYP1B1 drive an increase in the NAS/melatonin ratio in tumor-associated platelets will be interesting to determine." (PMID 36613754, 2022). "Additionally, CYP1B1 overexpression is also associated with increased tumor size, a higher tumor grade, frequent lymph node metastasis, and lymphovascular invasion." (PMID 33185690, 2020). "This study showed CYP1B1 gene G199T SNP could be useful to identify patients with a higher risk of tumor recurrence and death after surgical resection of NSCLC and thereby help to select patients for preoperative or postoperative drug adjuvant therapies." (PMID 28377924, 2017). "We also found that these anti-tumor effects on RCC cells caused by CYP1B1 depletion may be due to alteration of CDC20 and DAPK1 expression based on gene microarray and confirmed by real-time PCR." (PMID 26626260, 2015). "Interestingly, CYP1B1 expression was associated with tumor grade and stage." (PMID 26626260, 2015). "Individual reports have recently shown that CYP1B1 is likely to affect tumor progression by regulating ferroptosis level." (PMID 39478199, 2025). "RNA-seq identified robust induction of xenobiotic metabolism (CYP1A1, CYP1B1), oxidative/metabolic stress mediators (GDF15, TIPARP), and tumour-associated genes (FOSB, VGF), alongside repression of tumour suppressors (FAT1, LINC00472)." (PMID 41600570, 2025). "To get better insight into the role of ADAM12 and CYP1B1 in the tumor–stroma crosstalk, first, we analyzed the influence of their silencing on RCC cell proliferation." (PMID 39806854, 2025). "Cytochrome P450 1B1 (CYP1B1) is a heme-containing enzyme involved in procarcinogen activation and estrogen metabolism, contributing to tumor progression." (PMID 40883330, 2025). "The mechanistic studies demonstrated that the quinone derivative DMAKO-20 underwent tumor-specific CYP1B1-catalyzed oxidation to produce active naphthoquinone mono-oximes and nitric oxide, which exhibited synergistic anticancer effects." (PMID 40143127, 2025). "Small-molecule inhibitors, including AKR1B10 inhibitors (e.g., statil, epalrestatl) 43 and CYP1B1 inhibitors (e.g., flavonoids, trans-stilbenes) 44, have shown preclinical efficacy in suppressing tumor growth." (PMID 39744163, 2025). "Molecular docking studies revealed that DMAKO-20 selectively interacts with CYP1B1, demonstrating strong binding affinity and tumor-specific oxidation, which enhances its anticancer effects." (PMID 40143127, 2025). "Resveratrol and other polyphenols, for example, have been examined for their ability to inhibit CYP1B1 in tumor cells and potentially restore drug sensitivity." (PMID 40883330, 2025). "Transcriptomic and genomic profiling revealed that CYP1B1 overexpression in resistant tumours functionally contributes to enhanced angiogenic potential and maintenance of the resistant phenotype." (PMID 40435846, 2025). "CYP4Z1 and CYP1B1 were highly expressed in malignant tissues compared to normal controls; expression correlated with higher tumor grade, suggesting their potential role as prognostic biomarkers for recurrence and therapeutic targets." (PMID 41404236, 2025). "Despite the absence of a statistically significant difference in CYP1B1 expression, a trend of increasing CYP1B1 expression was observed with increasing tumor size, grade, and stage." (PMID 41155673, 2025). "Among the 16 TNBC core biopsy samples subjected to nanoLC/MS-MS, both antibodies produced cytoplasmic staining in tumor cells which correlated well with CYP1B1 abundance values determined by MS via label free quantification (LFQ)." (PMID 40478625, 2025). "Compared with control LNCaP xenografts, LM10-treated xenografts also significantly reduced the mRNA levels of TDO2, AhR, CYP1A1 and CYP1B1 in castration-recurrent tumours." (PMID 40759641, 2025).
tumor (continued). "Through an in-depth analysis of the TCGA database, we found that the CYP1B1 expression level was positively correlated with tumour stage, lymphatic metastasis, and metastatic stage." (PMID 40435846, 2025). "After 24 days, the mice were euthanized, and the tumor weight of the sh‐Ctrl group was significantly heavier than that of the CYP1B1 knockdown group." (PMID 40263929, 2025). "PARPα induces the downregulation of CYP2S1 and CYP1B1 expression, which leads to tumor cycle arrest, the induction of apoptosis, and the reduction of tumor cell migration, inhibiting metastatic development." (PMID 40005270, 2025). "When tumor cell CYP1B1 was quantified by the weighted histoscore method, the distribution of CYP1B1 histoscores across the 80-sample TNBC cohort was bimodal." (PMID 40478625, 2025). "The protein–protein interaction network further underscores CYP1B1’s centrality in xenobiotic metabolism, estrogen regulation, and oxidative stress pathways, which are hallmarks of tumor biology." (PMID 41155673, 2025). "Cytochrome P450 1B1 (CYP1B1) is a monooxygenase involved phase I metabolism and is expressed in a variety of tumor tissues." (PMID 39596349, 2024). "Compared with those in the control group, the tumours that formed when CYP1B1 knockdown UMUC3 cells were injected subcutaneously into nude mice were smaller in size and lighter in weight." (PMID 38429911, 2024). "CYP1B1 is involved in the metabolism of xenobiotics and endogenous substances and exhibits higher expression in tumor cells than in the surrounding normal tissues." (PMID 38419527, 2024). "Metabolic genes CYP1B1, AANAT, ADH5, and ALDH3A2, associated with the serotonin and melatonin biosynthesis pathway, contribute to tumour growth, immune modulation, and altered metabolic states in the TME." (PMID 39457550, 2024). "CYP1A1 and CYP1B1 have a central role in tumor development and the activation step of pro-carcinogen compounds such as BaP." (PMID 39200369, 2024). "In tumor tissues, venous endothelial cells exhibited higher expression of metabolism-related genes such as CYP1B1 and PTGDS, the heightened expression of these genes was associated with poorer prognostic outcomes." (PMID 38414015, 2024). "CYP1B1 is thought to play a role in early embryonic development, but in adults is a marker for tumour development." (PMID 38257336, 2024). "It is also well known that CYP1A1 and CYP1B1 have important roles in tumor development (cell invasion, migration, and disease progression), in part linked to their metabolic activation by BaP." (PMID 39200369, 2024). "The results revealed that in comparison with the normal tissues, tumor tissues from ccRCC patients exhibited obviously high CYP1B1, KMO, and TDO2 staining." (PMID 38183155, 2024). "Among different cell types in the human HCC TME, CYP1B1 was expressed by CAF, TAM (tumor-associated macrophages), and TEC (tumor-associated endothelial cells)." (PMID 37156770, 2023). "We suggest that LTB4R2 activation by 12-HHTrE produced by aHSC CYP1B1 causes CTNNB1 activation via GSK3β pathway and subsequent YAP1 transcription and tumor promotion." (PMID 37156770, 2023). "Mechanistically, CYP1B1 induced tumor cell resistance to ferroptosis by increasing ACSL4 ubiquitination and promoting its degradation." (PMID 37059712, 2023). "Another study found that CYP1B1, as an enzyme with a unique tumor-specific expression pattern, can bioactivate a wide range of carcinogenic compounds." (PMID 37935887, 2023). "The expression of both Cyp1a1 and Cyp1b1 was upregulated in MEPs isolated from MC38 or E0771 tumor-bearing mice compared to in control healthy mice." (PMID 37919525, 2023). "Numerous CYP1B1 inhibitors have been developed to overcome treatment resistance in several tumor cell lines, and this strategy is recognized as the main therapeutic paradigm to treat malignancy." (PMID 36131924, 2022).
tumor (continued). "Several studies have highlighted a role for CYP1B1 in tumor growth and treatment resistance, suggesting that CYP1B1 is a potential oncological therapeutic target." (PMID 36131924, 2022). "These authors showed CYP1B1 to be correlated with tumor grade, clinical stage, immune cell subtype infiltration, tumor mutation burden, and DNA sequence microsatellite instability, as well as therapeutic resistance." (PMID 36613754, 2022). "Studies have shown that CYP1B1 inhibitors can block the activation of multiple proinflammatory signaling pathways in tumor cells and in the tumor microenvironment." (PMID 35292057, 2022). "Of the 16 metabolism-related genes, we found that AOC2, IDUA, GPC2, CSPG4, TPST1, and CYP1B1 were differentially expressed between tumor and normal tissue at the protein level according to the Human Protein Atlas (HPA) cohort." (PMID 35281080, 2022). "Does tumor-derived kynurenine drive platelet AhR/CYP1B1 to increase the NAS/melatonin ratio, with the autocrine effects of NAS activating the truncated TrkB-T, leading to platelet release of pro-inflammatory cytokines and pro-angiogenic factors ?" (PMID 36613754, 2022). "Collectively, these results indicate that CYP1B1 deserves additional study as an independent driver of aggressive tumor characteristics in TNBC." (PMID 36077068, 2022). "Of the 16 metabolism-related genes, we found AOC2, IDUA, GPC2, CSPG4, TPST1, and CYP1B1 to be differentially expressed between tumor and normal tissues at the protein level." (PMID 35281080, 2022). "Recent studies showed that CYP1B1 was involved in the drug resistance of tumor cells, such as paclitaxel and docetaxel." (PMID 36428734, 2022). "Intriguingly, overexpression of CYP1B1 was found to decrease the sensitivity of tumor cells to anticancer drugs such as paclitaxel and docetaxel, resulting in drug resistance." (PMID 34636736, 2021). "Several studies have emphasized the role of CYP1B1 in tumor progression and treatment resistance, recommending CYP1B1 as a novel oncological therapeutic target." (PMID 34884615, 2021). "With CYP1B1, moderate expression was identified in 21% of the normal tissues, 34% of the primary tumours and 30% of the metastatic samples, with just 3% of tumours showing high expression of CYP1B1." (PMID 34556703, 2021). "The development of several CYP1B1 inhibitors has been proposed to overcome treatment resistance in number of tumor cell lines and is regarded as the predominant therapeutic paradigm to treat malignancy." (PMID 34884615, 2021). "Taken together, normal and tumor cervical tissues showed a significant difference in CYP1B1 expression (P=.01)." (PMID 34636736, 2021). "A positive correlation with increasing tumour grade has been observed with the expression of CYP4V2, CYP4X1 and CYP4Z1; while CYP1B1, CYP3A5 and CYP51 were significantly associated with the ER status of the tumour." (PMID 33809117, 2021). "For instance, CYP2W1, CYP1B1, CYP2C9, CYP2C8, CYP2J2, and CYP4A have been linked to tumor-specific expression." (PMID 31998435, 2020). "When carcinogenic materials were delivered into mice with CYP1B1 knockout, decreased tumor growth, and increased DNA adduct formation was observed." (PMID 32626511, 2020). "Similar levels of expression of the transduced gene, evaluated in tumours by RT-PCR, were observed in CYP1B1-WT and CYP1B1-VAR cells of both origins." (PMID 32565541, 2020). "While the CYP1 family members are expressed in extrahepatic tissues, CYP1B1 is different due to it being overexpressed in different tumor types compared to expression in normal tissues." (PMID 31998435, 2020). "The presence of CYP1B1 in tumor cells decreases the sensitivity of the cells to the cytotoxic effects of Cisplatin." (PMID 32626511, 2020). "In contrast, tumours were formed from as low as 10 injected cells in CYP1B1-VAR cells (p < 10−4 when compared with CYP1B1-WT cells) and, as expected, tumour uptake from ALDH+ cells was significantly higher than from ALDH− cells (p = 0.0015)." (PMID 32565541, 2020).
tumor (continued). "Silencing CYP1B1 expression via shRNA resulted in increased caspase-1 expression, and attenuated tumor growth and progression in an in vivo mouse model." (PMID 32581794, 2020). "CYP1A1 was undetectable in normal and tumor samples, whereas CYP1B1 expression was significantly higher in PTC than in normal thyroid with median difference of 1.27 (range 0.10–20.87, p = 0.0004)." (PMID 31936153, 2020). "CYP1B1-mediated inflammation, which has deleterious effects on the cardiovascular system, can also contribute to carcinogenesis and tumor progression." (PMID 33185690, 2020). "Similar results were obtained for the CAL33 tumours, but the difference between control and CYP1B1-expressing tumours was only significant after 25 days; a significant difference was observed between CYP1B1-WT and CYP1B1-VAR." (PMID 32565541, 2020). "The recombinant lentivirus expressing CYP1B1 shRNA was intratumorally injected into established tumors or tumor cells expressing CYP1B1 shRNA were injected into nude mice." (PMID 28388569, 2017). "The average tumor size after 5 weeks of control shRNA injection was 595.7±102.6 mm3 compared to 249.3±46.6 mm3 in tumors treated with CYP1B1 shRNA." (PMID 28388569, 2017). "The average tumor size after 5 weeks was 792.5±116.2 mm3 in PC-3/control shRNA cells and 240.0±81.9 mm3 in tumors stably expressing CYP1B1 shRNA #4-2." (PMID 28388569, 2017). "Then, in order to evaluate the role of CYP1B1 in tumor growth in vivo, 45-day-old female nude mice were injected with MDA-MB-231 cells into the mammary fat pad region and treated with vehicle, G-1 and TMS alone or in combination." (PMID 29290975, 2017). "Elevated AhR and CYP1B1 gene expression reported before tumor formation in a rat model of mammary tumorigenesis suggested differential CYP1B1 regulation by a constitutively active AhR." (PMID 28671964, 2017). "Tumor cells containing CYP1B1 shRNA displayed a significant difference in the number of Ki67-positive cells compared to cells harboring control shRNA." (PMID 28388569, 2017). "We report that the CYP genes with highest expression, ranked by the mean expression in tumor tissues for all patients, are: CYP1B1 (mean normalized expression 112.8), CYP4Z1 (92.2), CYP2A6 (75.7), CYP4X1 (65.1), CYP4B1 (31.5), CYP2A7 (30.8), and CYP4F8 (11.6)." (PMID 28684774, 2017). "To determine the impact of CASP1 on the CYP1B1 inhibition-mediated anti-tumor effect, we examined the rate of cell proliferation and apoptosis." (PMID 28388569, 2017). "We also presented data indicating the feasibility of using in vivo lentivirus-delivered CYP1B1 shRNA to reduce the tumor burden in animals." (PMID 28388569, 2017). "The cytP450 was selected as the CYP1B1, due to its eukaryotic origin and its importance as a tumour suppressor, although both 1B1 and 1A2 isoenzymes produce a second tetrahydroxystilbene product, not structurally well characterized, named M1." (PMID 26947765, 2016). "This decrease in tumor outgrowth was accompanied by a decrease in Cyp1b1, Aldh1a1, and Sox2 expression, further linking AHR activity to expression of these genes." (PMID 26984638, 2016). "RCC tumors with strong CYP1B1 expression showed low miR-200c levels (1.87 ± 0.36 versus 5.14 ± 0.58 in tumor samples with weak CYP1B1 expression)." (PMID 25860934, 2015). "We studied the association between tumor pathology and the expression profile of seven phase I and II drug metabolizing genes (CYP1A1, CYP1B1, ALDH3A1, AOX1, GSTP1, GSTT1 and GSTM3) and some of their proteins." (PMID 26580399, 2015). "Our results demonstrate that CYP1B1 can be a potential tumor biomarker and a target for anticancer therapy in RCC." (PMID 26626260, 2015). "Genes in the second group, similar to the CYP1B1 gene, showed stable methylation statuses among normal livers but were hypermethylated in tumor cells." (PMID 26421064, 2015).
tumor (continued). "CYP1B1 has been found to have an effect on tumor response to anticancer drugs, such as cyclophosphamide, PTX and DTX, which consequently affects pharmacokinetics and the therapeutic efficacy of the drugs." (PMID 25516145, 2015). "Only by Western blot we detect major CYP1B1 protein level in tumor samples than normal adjacent samples in two patients." (PMID 24699256, 2014). "In contrast CYP1B1 appears to be present in a wide variety of tumors, but we did not detect any major differences in CYP1B1 mRNA expression between non-tumor and corresponding tumor tissues." (PMID 24699256, 2014). "The rest of the CYPs studied (CYP1A1, CYP1A2 and CYP1B1) showed similar mRNA relative expression levels between tumor and corresponding normal tissues." (PMID 24699256, 2014). "Although previous studies have investigated P450 expression in tumours and shown tumour selective expression of individual P450s most notably CYP1B1 the CYP26 family of P450s has received little prior attention in relation to their expression in tumours." (PMID 24608339, 2014). "In HepG2 cell culture media, dasatinib is removed by all tumor-expressed CYP with the following clearance rate: CYP2J2>CYP1A1>CYP1B1." (PMID 24819355, 2014). "CYP1B1 mRNA expression was detected in 12/13 normal and 11/13 paired tumor tissue samples (92% and 84%, respectively)." (PMID 24699256, 2014). "All of 20 matched tumor and normal bladder tissue pairs analyzed expressed detectable levels of CYP1B1 and CYP1A1 mRNA." (PMID 24358191, 2013). "CYP1A1 and CYP1B1 mRNA showed statistically significant upregulation across the tumor counterpart in 13/20 pairs respectively, as determined by qPCR." (PMID 24358191, 2013). "This corresponds to an approximate 65% overexpression of CYP1A1 and CYP1B1 mRNA respectively in the tumor tissues." (PMID 24358191, 2013). "4/20 and 5/20 tumor tissues revealed significant downregulations of CYP1B1 and CYP1A1 mRNA respectively, whereas in patients 13 and 17 the expression levels of CYP1A1 mRNA between tumor and normal tissue did not reveal a significant change." (PMID 24358191, 2013). "The modification in the expression levels of CYP1B1 has been shown to modulate tumor progression and thus specific inhibitors are expected to be of therapeutic/preventive benefit." (PMID 22686946, 2012). "Findings of the over-expression of CYP1B1 in many tumor tissues compared with normal surrounding cells have led to the search for prodrugs reliant on CYP1B1 metabolism for the conversion into cytotoxic therapeutics." (PMID 22686946, 2012). "On the whole, 92.86% (26/28) of the cases showed a clear-cut downregulation of CYP1B1 in tumor tissues as compared to their matched normal tissues." (PMID 22114726, 2011). "Although previous studies have suggested CYP1B1 protein expression to be tumor specific, our observations clearly indicate that the protein is not only expressed in normal as well as tumor tissues, but is also downregulated in oral tumor tissues." (PMID 22114726, 2011). "On the whole, CYP1B1 protein was downregulated in 19/21 tumor tissues in comparison to their corresponding normal tissues." (PMID 22114726, 2011). "The tumor-specific expression pattern of CYP1B1 has been suggested to be exploited for the development of targeted anticancer therapies." (PMID 22114726, 2011). "Ours is the only study documenting the CYP1B1 downregulation in matched tumor and normal OSCC samples at both the transcriptional and the translational levels." (PMID 22114726, 2011). "In patient 226, CYP1B1 was upregulated at the mRNA level in the tumor tissue, but equal expression of CYP1B1 protein was observed in normal and tumor tissues." (PMID 22114726, 2011). "In patients 63 and 135, though the mRNA levels were higher in tumor tissues than their corresponding normal tissues, tumor tissues showed downregulation of CYP1B1 at the protein level." (PMID 22114726, 2011).